RNU6-444P (RNA, U6 small nuclear 444, pseudogene)
Gene: Small nuclear RNA gene on chromosome 6 (87,488,445 to 87,488,552, forward strand). Ensembl gene ENSG00000206715.
Homologues: Orthologues: chimpanzee U6 (99% identical), guinea pig U6 (86% identical), macaque U6 (80% identical). Paralogues in human: RNU6-16P (86% identical), RNU6-41P (86% identical), RNU6-812P (86% identical), RNU6-1131P (85% identical), RNU6-11P (85% identical), RNU6-37P (85% identical), RNU6-393P (85% identical), RNU6-73P (85% identical), RNU6-832P (85% identical), RNU6-921P (85% identical), RNU6-1145P (84% identical), RNU6-115P (84% identical), and 1289 more.